SERPINB1 (serpin family B member 1)
Diseases named in the same sentence as SERPINB1 in open-access papers (continued):
Sharing a sentence is not in itself a finding about the gene and the disease.
amyloidosis (1 paper, 2022). A disorder characterized by the localized or diffuse accumulation of amyloid protein in various anatomic sites. "In line with our results, genetic variation of SERPINB1 seems to be associated to amyloidosis in a sex-specific manner and, additionally, its expression in prefrontal cortex has been related to amyloid burden, further supporting the possible involvement of SERPINB1 in neurodegeneration." (PMID 35416570, 2022).
apical periodontitis (1 paper, 2019). "Accordingly, a significant increase in heat shock protein 27 (HSP27) and Serpin Family B member 1 (SERPINB1) protein levels were identified in apical periodontitis compared to healthy tissues." (PMID 31379856, 2019).
Ataxia (1 paper, 2025). Ataxia refers to impaired coordination of voluntary muscle movement. "Besides, a trend was observed for decreasing SERPINB1 plasma levels along with advancing disease stages, from mild (mean: 4.179 ng/ml), to moderate (mean: 3.886 ng/ml), to severe ataxia (mean: 2.593 ng/ml), though not statistically significant (F = 1.544; p = 0.221)." (PMID 41298695, 2025).
Bowen’s disease (1 paper, 2022). "Furthermore, the relative expression levels of TNC, FSCN1, SERPINB1 in the Bowen disease were also significantly increased, while the COL3A1 were also significantly decreased relative to the healthy control." (PMID 36085041, 2022). "Our study revealed that higher expression of SERPINB1 in CSCC relative to Bowen disease." (PMID 36085041, 2022). "And next, among 20 proteins, 8 proteins (TNC, FSCN1, SERPINB1, ACTN1, RAB31, COL3A1, COL1A1 and CD36) expressed levels showed significant differences between CSCC and Bowen disease." (PMID 36085041, 2022). "Besides, the proteins of TNC, FSCN1, SERPINB1, ACTN1 and RAB31 in CSCC were significantly up-regulated, while COL3A1, COL1A1 and CD36 were significantly down-regulated relative to Bowen disease in proteomics results." (PMID 36085041, 2022).
brain cancer (1 paper, 2021). A primary or metastatic malignant neoplasm affecting the brain. "SERPINB1 abundance was independent of mortality in patients with brain cancer." (PMID 34066760, 2021).
brain tumors (1 paper, 2016). "We show that brain tumors can acquire expression of SERPINB1, SERPINB4, and SERPINB9 as a potential mechanism to resist granzyme-induced cytotoxicity." (PMID 26963506, 2016).
chronic obstructive pulmonary disease (1 paper, 2022). A chronic and progressive lung disorder characterized by the loss of elasticity of the bronchial tree and the air sacs, destruction of the air sacs wall, thickening of the bronchial wall, and mucous accumulation in the bronchial tree. "In a previous study, human serpins α1-PI, serpinB1, and secretory leukocyte inhibitor (SLPI) blocked NSPs, particularly NE, which reduced inflammation-related severity and excessive elastase-induced tissue damage in a mouse model of chronic obstructive pulmonary disease (COPD)." (PMID 36389172, 2022).
influenza infection (1 paper, 2023). "For example, SERPINB1 has been reported to influence the innate immune system during influenza infection, PTCH1 is important for macrophage chemotaxis during gastric inflammation, and PSAT1 regulates the inflammatory response in macrophages." (PMID 36761770, 2023).
intracerebral hemorrhage (1 paper, 2025). A cerebrovascular disorder characterized by bleeding into one or both cerebral hemispheres including the basal ganglia and the cerebral cortex. "We found significant overlap with gene lists associated with intracerebral hemorrhage (ICH) volume (SERPINB1, TSPO, and GSR) and absolute perihematomal edema (PHE; TSPO and GSR) volume in ICH patients." (PMID 41353157, 2025).
neutropenia (1 paper, 2025). A decrease in the number of neutrophils found in the blood. "Serpin family B member 1 (SERPINB1) protects neutrophils by inhibiting CG, which is verified by the fact that SERPINB1-deficient mice with bone marrow neutropenia reach complete remission by genetic deletion of CG, but not neutrophil elastase (NE)." (PMID 39800780, 2025).
Obesity (1 paper, 2022). Accumulation of substantial excess body fat. "In conclusion, in Japanese T2DM subjects with less severe obesity, serum SerpinB1 is positively correlated with insulin sensitivity and better blood glucose level." (PMID 36331940, 2022).
postmenopausal osteoporosis (1 paper, 2021). Metabolic disorder associated with fractures of the femoral neck, vertebrae, and distal forearm. "In that study, Serpinb1 variants in osteoclasts were derived from patients with postmenopausal osteoporosis." (PMID 33997318, 2021).
primitive neuroectodermal tumor (1 paper, 2023). A malignant neoplasm that originates in the neuroectoderm. "In MB and in primitive neuroectodermal tumors (PNET), the granzyme inhibitors SERPINB1 and SERPINB4 were acquired in 23% and 50% of the MB, respectively, while PNETs expressed SERPINB9, SERPINB1, and SERPINB4 in 29%, 29%, and 57% of the tumors." (PMID 37509316, 2023).
prion disease (1 paper, 2022). A transmissible disease that is caused by a protein that is able to induce abnormal folding of normal cellular proteins, leading to characteristic spongiform brain changes, which are associated with neuronal loss without an inflammatory response. "Our analysis revealed that, besides the already observed upregulation of SERPINA3 in patients with prion disease and AD, SERPINB1, SERPINB6, SERPING1, SERPINH1, and SERPINI1 were dysregulated in sCJD individuals compared to controls, while only SERPINB1 was upregulated in AD patients." (PMID 35416570, 2022).
psoriasis (1 paper, 2024). An autoimmune condition characterized by red, well-delineated plaques with silvery scales that are usually on the extensor surfaces and scalp. "Some anti-inflammatory serpins(SerpinB1, B2) are highly expressed in psoriasis, which may be the body’s response to the development of the disease." (PMID 39737188, 2024). "Like SerpinB2, B3, SerpinB1 is elevated in lesional skin of psoriasis patients." (PMID 39737188, 2024).
serous ovarian cancer (1 paper, 2021). "In the serous ovarian cancer patients of cohort 2 (n = 20/80), detectable antibodies (Z-scores > 0) were seen against CTAG2 (n = 3/20, 15%), SHARPIN (n = 2/20, 10%), PNMA2 (n = 2/20, 10%), MAGEB4 (n = 1/20, 5%), MRFAP1L1 (n = 1/20, 5%), SERPINB1 (n = 1/20, 5%) and XAGE3 (n = 1/20, 5%)." (PMID 34681879, 2021).
systemic lupus erythematosus (1 paper, 2025). An autoimmune multi-organ disease typically associated with vasculopathy and autoantibody production. "In systemic lupus erythematosus (SLE), FcγR activation downregulates SERPINB1 in neutrophils, leading to spontaneous activation of caspase-1/-11 and GSDMD cleavage." (PMID 39800780, 2025).
ulcerative colitis (1 paper, 2021). An inflammatory bowel disease involving the mucosal surface of the large intestine and rectum. "Studies on patients with ulcerative colitis have demonstrated the expression of SerpinB1 not only in inflammatory infiltrating cells, but also in colonic epithelial cells." (PMID 33473269, 2021).
vitamin D deficiency (1 paper, 2021). A nutritional condition produced by a deficiency of VITAMIN D in the diet, insufficient production of vitamin D in the skin, inadequate absorption of vitamin D from the diet, or abnormal conversion of vitamin D to its bioactive metabolites. "However, we previously observed that a vitamin D deficiency did not affect Serpinb1 mRNA levels in the tibia and gastrocnemius muscles of VD-deficient diet-fed mice (data not shown)." (PMID 33997318, 2021).
tumor (22 papers, 2010 to 2025). "All SERPINB families are associated with tumor cell invasion, with SERPINB1, SERPINB5 and SERPINB7 being more strongly associated with invasion." (PMID 37064125, 2023). "High SERPINB1 protein expression in tumor tissue from cisplatin-treated patients was associated with a favorable survival (p = 0.011), and proved as an independent predictor of survival (p = 0.008) by multivariate analysis." (PMID 26799424, 2016). "High SERPINB1 gene expression was associated with favorable tumor response (p = 0.012) and prolonged survival (p = 0.081) under cisplatin-based chemotherapy." (PMID 26799424, 2016). "Traditionally, SERPINB2, a secreted glycoprotein that inhibits tPA and urokinase, has been described as a tumor suppressor that inhibits tumor growth and metastasis, whereas SERPINB1 promotes tumor progression." (PMID 29404274, 2017). "The relative expression of SERPINB1 as measured by qPCR in cryopreserved tumor tissues from validation set 1 was correlated to the patients clinical outcome." (PMID 26799424, 2016). "In these cancer entities, it has been shown that SERPINB family members, particularly SERPINB1, –B5, and –B7, are differentially expressed in tumor tissues compared to matched normal tissues from the same patients." (PMID 26799424, 2016). "LEI (SERPINB1) was downregulated in tumor tissues, as shown by 2D-DIGE and further confirmed by western blot, unlike what has been reported by others." (PMID 21973086, 2011). "Importantly, SERPINB1 mRNA levels increased with disease severity in the Copenhagen cohort, being particularly overexpressed in advanced tumor stages compared with early stage CCAs." (PMID 32183400, 2020). "This study identified that a high expression of SERPINB1 is associated with a worse prognosis in HPV-positive patients and could be a mechanism of the tumor to escape from recognition or killing by the immune system." (PMID 26993499, 2016). "PUF60 contributes to apoptosis and transcriptional regulation, SFXN3 is a mitochondrial serine transporter, SERPINB1 regulates the innate immune response, SERPINB5 is a tumor suppressor, and STXBP2 regulates exocytosis." (PMID 36400567, 2023). "Conversely, genes with known tumor-suppressor properties were identified among the genes overexpressed in TumLOW cells (e.g. TUSC3, SERPINB1)." (PMID 31619292, 2019). "In this study, we compared tumor-infiltrating CD3+, CD4+, CD8+ T-cells, and granzyme inhibitors (SERPINB1, SERPINB4, and SERPINB9) between HPV-positive and HPV-negative tumors and the relation with survival." (PMID 26993499, 2016). "Indeed, this study revealed that three serpins secreted by cells in the tumor microenvironment (TME), including A1AT, SERPINB1, and SLPI, can antagonize ELANE’s anti-tumor capability in a dose-dependent manner." (PMID 34599140, 2021). "In the total group, HPV-positivity, small tumor size (T1–T2), no lymph node metastasis, high number of CD3+ and CD8+ intratumor cells, and a low expression of SERPINB1 in tumor cells were all individually significant associated with an improved OS." (PMID 26993499, 2016). "qPCR quantification of the relative expression of the five candidate genes LOXL1, SCRN1, VAMP5, SERPINB1, and TMSB4X in cryopreserved tumor tissues from validation set 1 was correlated to the CSIs measured in the corresponding fresh tissue samples of the same tumor lesions." (PMID 26799424, 2016). "Within tumor tissue in the adequate iron group, and more so in tumors from the excess iron diet group, we found there was also significantly greater (p ≤ 0.05) expression of proteins involved in protein degradation (ANPEP, DPP7, ITGB1, PSMA1, PSMA2, PSMA3, and SERPINB1)." (PMID 38732562, 2024). "Thus, our results clearly show, that SERPINB1 expression in tumor tissue is not prognostic, like the majority of the already tested potentially predictive markers, but predictive only." (PMID 26799424, 2016).
infection (13 papers, 2013 to 2023). The state of being infected such as from the introduction of a foreign agent such as serum, vaccine, antigenic substance or organism. "In a SERPINB1-deficient mice model study, SERPINB1 plays an important role in protecting lung antimicro proteins from proteases during infection." (PMID 36742332, 2023). "The results of previous research reported high levels of SERPINB1 in myeloid cells, especially neutrophils, the short-lived cells recruited immediately to infection sites to destroy pathogenic microbes." (PMID 36552219, 2022). "Expression of other genes that were strongly upregulated after infection with most mycobacteria included SERPINB1, CXCL2, CXCL8, CXCL10, and LCN2." (PMID 37822359, 2023). "This population includes several neutrophil-associated genes (OLFM4, CD177, SERPINB1, S100P, PTX3 and MMP8), suggesting that there is an accumulation of neutrophils in PBCMs during the course of infection." (PMID 27595844, 2016). "Therefore, the modulation of SERPINB1 expression represents an important mechanism to minimize host damage from exacerbated inflammatory response against infection." (PMID 33868226, 2021). "These include three proteases that are upregulated during the course of infection: the matrix metalloprotease MMP9, the serine proteases neutrophil elastase (ELANE), and cathepsin G (CTSG), as well as the protease inhibitor SERPINB1." (PMID 23638192, 2013). "HiRIEF LC-MS/MS detected alterations in the remaining proteins, i.e., ISG20, PSMB8, PSMB10, ALDOC, and SERPINB1, emphasising the method’s ability to capture alterations deriving from infection that are not picked up by other methods." (PMID 37739942, 2023). "Therefore, SERPINB1 may represent a novel target for further study of its potential to neutralize HIV, thus preventing infection." (PMID 26090884, 2015).
cancer (12 papers, 2010 to 2025). A tumor composed of atypical neoplastic, often pleomorphic cells that invade other tissues. "While the roles of C4BPB, HLA-C, and SERPINB1 in cancer immunobiology have been increasingly recognized, direct evidence of their function in PDAC remains limited." (PMID 41007761, 2025). "Since SERPINB1 assists in protease inhibition, dysregulation may allow cellular protein degradation to persist unchecked, as seen in other cancer development pathways involving iron as a requirement for cellular growth." (PMID 38732562, 2024). "The role and specific function of SERPINB1 in cancer biology is largely unknown." (PMID 26799424, 2016).
SERPINB1 also shares sentences with these, for which no sentence is quoted: COVID-19 (4 papers); Stroke (4); autism spectrum disorder (2); bacterial infections (2); depression (2); epilepsy (2); Hyperglycemia (2); Hyperinsulinemia (2); mental disorder (2); Anxiety (1); asthma (1); breast tumors (1); colitis (1); cutaneous melanoma (1); dyslipidemia (1); Gestational Diabetes Mellitus (1); hepatitis B (1); hyperlipidemia (1); infectious disease (1); neurological diseases (1); osteosarcoma (1); otitis media (1); ovarian carcinoma (1); periodontitis (1); prostate tumor (1); schizophrenia (1); spinocerebellar ataxia type 2 (1); sporadic Creutzfeldt-Jakob disease (1); tuberculosis (1).